TMSB15A (thymosin beta 15A)
Description:
Plays an important role in the organization of the cytoskeleton. Binds to and sequesters actin monomers (G actin) and therefore inhibits actin polymerization.
Synonyms: TMSL8; TMSNB; TMSB15; Tb15; TbNB
Tractability: No criterion of Open Targets' tractability assessment is met for any kind of drug.
Gene: Protein-coding gene on chromosome X (102,513,674 to 102,516,795, reverse strand). Ensembl gene ENSG00000158164.
Subcellular location: Cytoplasm, cytoskeleton
Gene Ontology:
Molecular function: actin monomer binding; protein sequestering activity
Biological process: regulation of cell migration; actin filament organization
Cellular component: filamentous actin; cytoskeleton
Homologues: Orthologues: chimpanzee TMSB15A (100% identical). Paralogues in human: TMSB15B (100% identical), TMSB15C (100% identical).
Diseases named in the same sentence as TMSB15A in open-access papers:
TMSB15A is named in the same sentence as 8 diseases in open-access papers, as found by Europe PMC text mining. Sharing a sentence is not in itself a finding about the gene and the disease. The quoted sentences say what the papers report.
prostate carcinoma (3 papers, 2009 to 2025). A carcinoma that arises from epithelial cells of the prostate gland. "Among these, two homeobox genes, HOXC10 and HOXD10, and TMSB15A, encoding for thymosin-beta-15A, a tumor motility gene promoting metastases in prostate cancer, all overexpressed in STCs vs LTCs." (PMID 26188123, 2015). "In the Prostate Cancer dataset, we identified some important genes with significant biological relevance, such as TMSB15A, PEDF, hepsin, KIAA0977, and S100A4." (PMID 19874631, 2009).
breast carcinoma (1 paper, 2019). "Interestingly, AK291479 overlaps with the transcript of thymosin beta-15B (TMSB15B), one of the two isoforms of human thymosin beta 15, TMSB15A and TMSB15B, which show approximately equivalent levels of expression in MCF-7 breast cancer cells." (PMID 31191314, 2019).
glioma (1 paper, 2023). A benign or malignant brain and spinal cord tumor that arises from glial cells (astrocytes, oligodendrocytes, ependymal cells). "Among them, IFNGR2, TXLNA, PSMC2, and TMSB15A have not been reported to be associated with gliomas." (PMID 37867596, 2023).
neuroblastoma (1 paper, 2023). Neuroblastoma (NB) is the most common solid, extracranial childhood tumor. "Conversely, a transcriptomic study on neuroblastoma SK-N-SH cells revealed that SARS-CoV-2 infection induced a downregulation of several members of building blocks of the cytoskeleton, as well as some of their regulators (i.e., TUBA1A, TUBA4A, TUBB4A, STMN4, TMSB15A, SYNPO2)." (PMID 37896797, 2023).
Parkinson disease (1 paper, 2025). A progressive degenerative disorder of the central nervous system characterized by loss of dopamine producing neurons in the substantia nigra and the presence of Lewy bodies in the substantia nigra and locus coeruleus. "In this study, we identified seven hub genes—PI3, TMSB15A, CLEC4M, CD4, SEMA6A, PLXND1, and AVP—that collectively drive Parkinson’s disease progression through synergistic mechanisms." (PMID 41329689, 2025).
triple-negative breast carcinoma (1 paper, 2019). An invasive breast carcinoma which is negative for expression of estrogen receptor (ER), progesterone receptor (PR), and human epidermal growth factor receptor 2 (HER2). "Moreover, it has been reported that thymosin beta 15A (TMSB15A) is a predictor of pCR of chemotherapy in triple-negative breast cancer." (PMID 31191314, 2019).
tumor (6 papers, 2009 to 2025). "DSEL, ID4, REEP2, and TMSB15A were upregulated in the NPC samples compared with the non-tumor samples." (PMID 38532632, 2024). "Furthermore, we found that the expression of TMSB10 in the tumor tissues was the highest among these seven TMSs, and TMSB15A, TMSB4Y and TMSB15B showed relatively low expression." (PMID 36163046, 2022). "A nomogram was constructed using the expressions of LINC01116, TMSB15A and HBV status, and tumor stage and radical resection based on the different points of each factor." (PMID 37340445, 2023). "Compared to non-tumor samples, REEP2, TMSB15A, DSEL, and ID4 were upregulated in NPC samples." (PMID 38532632, 2024). "However, the expression of DSEL, ID4, REEP2, and TMSB15A not related the tumor progression." (PMID 38532632, 2024).
cancer (4 papers, 2022 to 2024). A tumor composed of atypical neoplastic, often pleomorphic cells that invade other tissues. "Most of these CAF-related genes are associated with tumorigenesis and cancer progression, including GLT8D1, GPX3, NRP1, PPP1R26, SERPINE1, and TMSB15A." (PMID 36717783, 2023). "TMSB15A has been reported to be upregulated in TNBC; it plays a crucial role in the organization of the cytoskeleton, which is responsible for cancer cell motility and is involved in cancer metastasis." (PMID 37900178, 2023).